RNU7-159P (RNA, U7 small nuclear 159 pseudogene)
Gene: Small nuclear RNA gene on chromosome 11 (102,903,892 to 102,903,953, reverse strand). Ensembl gene ENSG00000238562.
Homologues: Orthologues: chimpanzee U7 (100% identical), macaque U7 (61% identical), macaque U7 (60% identical). Paralogues in human: RNU7-75P (76% identical), RNU7-19P (73% identical), RNU7-20P (73% identical), RNU7-63P (73% identical), RNU7-73P (73% identical), RNU7-1 (71% identical), RNU7-38P (71% identical), RNU7-7P (71% identical), U7 (71% identical), RNU7-107P (69% identical), RNU7-11P (69% identical), RNU7-136P (69% identical), and 143 more.